DLEU2 (deleted in lymphocytic leukemia 2)
Diseases named in the same sentence as DLEU2 in open-access papers (continued):
Sharing a sentence is not in itself a finding about the gene and the disease.
laryngeal squamous cell carcinoma (5 papers, 2020 to 2024). A squamous cell carcinoma that arises from the larynx. "For example, the overexpression of DLEU2 (lncRNA) functions as an adsorbed RNA that suppresses miR-30c-5p and subsequently activates the Akt signaling pathway in laryngeal squamous cell carcinomas." (PMID 32977589, 2020). "In laryngeal squamous cell carcinoma, lncRNA DLEU2 affects cell proliferation and cell cycle." (PMID 38296962, 2024).
lymphocytic leukemia (5 papers, 2017 to 2024). "Of seven lncRNAs with a degree >100, only DLEU2 (Deleted in Lymphocytic leukemia 2) is well studied." (PMID 31852840, 2019). "DLEU2 is a lymphocytic leukemia-related gene and is the host gene promoter for miR-15a/16-1, and acts as ceRNA to sponge miRNA in clear cell renal cell carcinoma (ccRCC)." (PMID 29912172, 2018). "DLEU2 is a lymphocytic leukemia-related gene and the host gene promoter for miR-15a/16-1." (PMID 29912172, 2018).
clear cell renal cell carcinoma (3 papers, 2018 to 2020). "Moreover, the downregulated target of DLEU2, miR-30a-5p, suppresses the epithelial–mesenchymal transition in clear cell renal cell carcinoma via the repression of ZEB238." (PMID 32555190, 2020).
endometrial cancer (3 papers, 2022 to 2024). Primary or metastatic malignant neoplasm involving the endometrium (mucous membrane that lines the endometrial cavity). "DLEU2 has been reported to play a crucial role in the progression of cancers such as the case of liver cancer and endometrial cancer." (PMID 37476628, 2023). "For example, Lnc-DLEU2 can drive epithelial-mesenchymal transition and glycolysis in endometrial cancer through HK2 by competitively binding to miR-455 and by modulating the enhancer of zeste 2 polycomb repressive complex 2 subunit (EZH2)/miR-181 pathway." (PMID 35156508, 2022).
esophageal cancer (3 papers, 2021 to 2022). A primary or metastatic malignant neoplasm involving the esophagus. "DLEU2 also promotes the proliferation, migration, and invasion of esophageal cancer cells via the miR-30e-5p/E2F transcription factor 7 axis." (PMID 35075115, 2022). "Furthermore, the lncRNA DLEU2 is overexpressed in esophageal cancer tissue and is related to poor prognosis in esophageal cancer patients." (PMID 35075115, 2022).
liver cancer (3 papers, 2021 to 2023). An epithelial or non-epithelial malignant neoplasm that arises from the liver. "The relationship between overexpression of DLEU2 and worse patient survival rate was also confirmed in esophageal, head-neck, kidney, liver cancers, and pheochromocytoma/paraganglioma." (PMID 34174908, 2021).
keloid (2 papers, 2020 to 2022). An irregularly shaped, elevated mark on the skin caused by deposits of excessive amounts of collagen during wound healing. "Therefore, DLEU2 was predicted to play an important role in keloid formation and wound healing through regulating fibroblast proliferation, differentiation, and apoptosis." (PMID 36046343, 2022). "The results showed that only the expression of DLEU2 and ADIRF-AS1 in keloid fibroblasts showed significant difference and that the expression of other genes was not changed significantly." (PMID 33203788, 2020). "Specifically, the expression of DLEU2 and ADIRF-AS1 were in significantly different expression levels between fibroblasts and keloid." (PMID 33203788, 2020). "Six lncRNAs, namely, 2 upregulated (DLEU2 and AP000317.2) and 4 downregulated (ADIRF-AS1, AC006333.2, AL137127.1 and LINC01725) lncRNAs, were expressed only in the keloid-prone group and were used to construct a ceRNA network." (PMID 33203788, 2020). "Furthermore, 6 lncRNAs, namely, 2 upregulated (DLEU2 and AP000317.2) and 4 downregulated (ADIRF-AS1, AC006333.2, AL137127.1 and LINC01725) lncRNAs, were expressed only in the keloid-prone group and were used to construct a ceRNA network." (PMID 36046343, 2022). "Moreover, the expression of DLEU2 and ADIRF-AS1 were significantly different in fibroblasts in keloid scars compared with the normal skin." (PMID 36046343, 2022). "Although these lncRNAs have not been reported in previous keloid-related literature, molecules such as DLEU2 and ADIRF-AS1 have been detected in other tissues and diseases." (PMID 33203788, 2020).
lung adenocarcinoma (2 papers, 2020 to 2024). A carcinoma that arises from the lung and is characterized by the presence of malignant glandular epithelial cells. "As shown by FISH analysis, we found that lncRNA DLEU2 expression, predominantly in the cytoplasm, was dramatically raised in lung adenocarcinoma (LAC) tissue samples compared with the normal tissues (n = 20, P < .0001)." (PMID 31721438, 2020). "In UALCAN cancer database, DLEU2 expression was higher in 533 lung adenocarcinoma tissues than in 59 noncancerous lung tissues." (PMID 38169645, 2024).
melanoma (2 papers, 2021 to 2024). A malignant, usually aggressive tumor composed of atypical, neoplastic melanocytes. "Furthermore, DLEU2 expression is significantly decreased in melanoma samples compared to normal skin." (PMID 38792557, 2024).
multiple myeloma (2 papers, 2023). "Many lncRNAs, such as MALAT1, GAS5, DLEU2, and H19, have been reported to be involved in the diagnosis and progression of multiple myeloma (MM)." (PMID 36607351, 2023).
sarcopenia (2 papers, 2020 to 2022). Progressive decline in muscle mass due to aging which results in decreased functional capacity of muscles. "In this study, high expression of DLEU2 was considered to be one of the risk factors for sarcopenia in older people." (PMID 33221762, 2020). "SEPP1 and DLEU2 expression levels were higher in patients with sarcopenia than in patients without sarcopenia, while the expression levels of GFOD1, GOT1, SV2A, and miR-181a were significantly lower in patients with sarcopenia than in patients without sarcopenia." (PMID 33221762, 2020).
thyroid cancer (2 papers, 2022 to 2023). "In TC, DLEU2 promotes aerobic glycolysis of thyroid cancer cells through the miR-205-5p/TNFAIP8 signaling axis." (PMID 37095423, 2023).
autoimmune disease (1 paper, 2024). A disorder resulting from loss of function or tissue destruction of an organ or multiple organs, arising from humoral or cellular immune responses of the individual to their own tissue constituents. "Our findings offered a novel mechanism in the Treg cell polarization process, expanded the function of Dleu2 in immunity, and highlight the therapeutic potential of Dleu2-17aa in autoimmune disease." (PMID 38291338, 2024). "Our findings demonstrate an indispensable role of Dleu2-17aa in maintaining immune homeostasis and suggest therapeutic applications for this peptide in treating autoimmune diseases." (PMID 38291338, 2024). "We further showed that exogenously delivered Dleu2-17aa significantly alleviated EAE, which demonstrated its therapeutic potential for treating autoimmune diseases." (PMID 38291338, 2024). "Dleu2-17aa promotes Smad3 binding to the CNS1 region of Foxp3, regulates TGF-β/Smad signaling, and plays an anti-inflammatory role in autoimmune disease (Synopsis Fig)." (PMID 38291338, 2024).
breast tumors (1 paper, 2024). "Likewise, different clinical stages of breast tumors have varying levels of lncRNA DLEU2 expression." (PMID 38296962, 2024).
cardiomyopathy (1 paper, 2018). A disease of the heart muscle or myocardium proper. "Among them, DLEU2 was found to be contained in a deletion at chr13q14.3 in an earthquake-associated stress cardiomyopathy case, and this region including a gene play important roles in regulating voltage-gated potassium channel activity." (PMID 29531832, 2018).
cognitive decline (1 paper, 2023).
COVID-19 (1 paper, 2021). A disease caused by infection with severe acute respiratory syndrome coronavirus 2. "Interestingly we found six lncRNAs (TALAM1, DLEU2, and UICLM CASC18, SNHG20, and GNAS) involved in the protein-coding DEG-lncRNA network; which might be served as potential biomarkers for COVID-19 patients." (PMID 34975833, 2021).
esophageal squamous cell carcinoma (1 paper, 2023). Esophageal squamous cell carcinoma (ESCC) is a type of esophageal carcinoma (EC) that can affect any part of the esophagus, but is usually located in the upper or middle third. "The upregulation of DLEU2 promoted tumorigenesis of esophageal squamous cell carcinoma, which was epigenetically mediated by m6A demethylase FTO." (PMID 35789547, 2023).
experimental autoimmune encephalomyelitis (1 paper, 2024). An autoimmune demyelinating disease of the central nervous system that is produced experimentally in animals by the injection of homogenized brain or spinal cord in Freund's adjuvant. "Importantly, the genetic deletion of Dleu2-17aa in mice by start codon mutation impairs iTreg generation and worsens experimental autoimmune encephalomyelitis (EAE)." (PMID 38291338, 2024). "We generated start codon-mutated mice with Dleu2-17aa genetically ablated while the expression of its host gene unaffected and found that these mice were defective in generating iTreg cells and were thus more susceptible to experimental autoimmune encephalomyelitis (EAE)." (PMID 38291338, 2024).
lymph node metastasis (1 paper, 2020). "According to the univariate and multivariate analysis, we found that high DLEU2 expression as well as lymph node metastasis was an independent prognostic factor of poor survival in LAC patients." (PMID 31721438, 2020).
mantle cell lymphoma (1 paper, 2021). Mantle cell lymphoma is a rare form of malignant non-Hodgkin lymphoma affecting B lymphocytes in the lymph nodes in a region called the ``mantle zone''. "HDAC3 interacts with Myc through the MBIIIa domain, and subsequently reduces miR-15a/16-1 level in mantle cell lymphoma (MCL) by anchoring at the two promoters of the miR-15a/16-1 cluster gene, DLEU2, and exerting repressive function." (PMID 34658888, 2021).
multiple sclerosis (1 paper, 2024). A progressive autoimmune disorder affecting the central nervous system resulting in demyelination. "In our study, we showed that Dleu2-17aa treatment ameliorated EAE, a mouse model of multiple sclerosis, by reducing the numbers of inflammatory/effector CD4+ T cells and increasing the frequency of Treg cells in both the spleen and CNS of EAE mice." (PMID 38291338, 2024).
oral cancer (1 paper, 2022). "The aim of this study was to investigate the role of lncRNA deleted in lymphocytic leukemia 2 (DLEU2) in oral cancer." (PMID 36277988, 2022).
prostate tumor (1 paper, 2022). "First, we investigated the expression of DLEU2 in prostate tumor tissues from The Cancer Genome Atlas (TCGA) database." (PMID 35075115, 2022). "In vivo experiments indicated that DLEU2 knockdown suppressed prostate tumor growth." (PMID 35075115, 2022).
squamous cell carcinoma of the skin (1 paper, 2024). "Loss of the DLEU2 gene is associated with an increased risk of squamous cell carcinoma of the skin." (PMID 38792557, 2024).
tumor (43 papers, 2013 to 2025). "LncRNA DLEU2 is highly expressed in GC and is associated with poor tumor differentiation, elevated CA19‐9, and specific histologic classifications." (PMID 40740483, 2025). "In line with this, we further found that the expression of lncRNA DLEU2 was highly upregulated in therapy-resistant BC patients’ tumor tissues and associated with poor DFS." (PMID 38296962, 2024). "In this paper, we confirmed that DLEU2 induces promoter methylation and loss of expression of the tumor inhibitor RARB and enhanced viability and mobility of CRC cells through the activation of the MAPK pathway." (PMID 35611845, 2022). "Gain‐ and loss‐of‐function experiments as well as a NSCLC tumour model were executed to determine the role of lncRNA DLEU2 in NSCLC." (PMID 31721438, 2020). "Furthermore, abnormal lncRNA DLEU2 mutations play a crucial role in tumor progression in pancreatic, lung, and hematopoietic malignancies." (PMID 38296962, 2024). "Overall, LncRNAs including DLEU2 and HOTAIR are implicated in chromatin regulation, transcription regulation, and cell cycle constraining or enhancing tumor formation." (PMID 40625740, 2025). "Mechanistically, ROR1 and lncRNA DLEU2 overexpression led to enhanced tumor cell proliferation, inhibition of apoptosis, cell-cycle dysregulation, chemoresistance, as well as BC cell’s abilities to invade, migrate, develop spheroids." (PMID 38296962, 2024). "Collectively, the DLEU2/miR-212-5p/ELF3 pathway mediates the anti-tumor effects of Huaier by ultimately regulating proteins involved in migration and invasion." (PMID 38169645, 2024). "To explore the involvement of miR-212-5p in the anti-tumor effects of Huaier mediated by DLEU2, we cotransfected DLEU2 siRNA and miR-212-5p inhibitor or DLEU2 siRNA and inhibitor control into A549 cells." (PMID 38169645, 2024). "Conversely, overexpression of DLEU2 in Huaier-treated NSCLC cells counteracted the anti-tumor effects of Huaier, leading to increased colony formation capacity, migratory potential, and invasive ability." (PMID 38169645, 2024). "The findings suggest that the DLEU2/miR-212-5p/ELF3 axis plays a crucial role in mediating the anti-tumor effects of Huaier." (PMID 38169645, 2024). "MiR-212-5p functions as a downstream effector of DLEU2, and inhibition of miR-212-5p attenuates the anti-tumor effects elicited by downregulation of DLEU2 and treatment with Huaier." (PMID 38169645, 2024). "To clarify the ELF3 in the anti-tumor effects of Huaier mediated by DLEU2/MiR-212-5p, we cotransfected DLEU2 siRNA and pcDNA3.1-ELF3 or DLEU2 siRNA and vector control into A549 cells." (PMID 38169645, 2024). "In PC and NSCLC, transwell assays showed that DLEU2 knockdown reduced the invasion ability of tumor cells." (PMID 37095423, 2023). "DLEU2 negatively correlates with miR-30a-5p expression in NSCLC tissues and acts as a sponge for miR-30a-5p, reversing the tumor-promoting effects of DLEU2 by targeting PHTF2." (PMID 37095423, 2023). "DNA demethylation level was positively correlated with the expression of DLEU1 and DLEU2, albeit negatively with the expression of neighboring tumor-suppressors, suggesting in cis co-regulation of these genes and their functional connection." (PMID 36362925, 2022). "Additional studies will be needed to clarify the functional contribution of DLEU2 in cancer biology, the precise mechanisms downstream of DLEU2, and how its expression is regulated in tumor cells." (PMID 34174908, 2021). "Previous studies on DLEU2 have mainly focused on its oncogenic role in controlling tumor cell proliferation, migration, and invasion." (PMID 34174908, 2021). "lncRNA DLEU2 was significantly upregulated in CRC tissues compared with non-tumor tissues (p < 0.05)." (PMID 33391439, 2021). "Other studies using the same method to knock down and exogenously express DLEU2 in other types of tumor cells resulted in similar conclusions that DLEU2 promotes the malignant proliferation of tumor cells." (PMID 34261460, 2021).
tumor (continued). "The mice receiving combined treatment of DLEU2 expression knockdown and TX treatment demonstrated a much smaller tumor volume and weight than the other mice." (PMID 34174908, 2021). "Based on MYCN and DLEU2 expression in NB patients, survival curves were plotted and survival probability was estimated (Tumor NB public‐Versteeg‐88‐MAS5.0‐u133p2)." (PMID 31637848, 2020). "Statistically significant correlations were found between high levels of DLEU2 expression and an advanced tumor stage (P = 0.022), lymph node metastasis (P = 0.010), and an advanced tumor node metastasis (TNM) stage (P = 0.005)." (PMID 32555190, 2020). "The results indicated that DLEU2 was significantly upregulated in the tumor tissues, compared with the normal tissues." (PMID 32555190, 2020). "The inverse correlation between MYCN and DLEU2, the host gene for miR‐15 family, in NB patient tumor samples clearly demonstrate that MYCN regulation is through these miRs." (PMID 31637848, 2020). "In these studies, DLEU2 was shown to be essential in modulating the proliferation, invasion, and migration of tumor cells." (PMID 32555190, 2020). "The results indicated that DLEU2 overexpression significantly enhanced the vitality of the tumor cells, while DLEU2 knockdown suppressed it." (PMID 32555190, 2020). "Further, we investigated the relationship between the expression of MYCN and DLEU2 in an independent set of NB primary tumors (Tumor NB public‐Westermann‐105‐ag44kcwolf) using the R2 database." (PMID 31637848, 2020). "By comparing clinicopathological characteristics, High expression of lncRNA DLEU2 significantly correlated with tumor size, advanced TNM stage (III+IV), and metastasis (p<0.05, p<0.01)." (PMID 31541993, 2019). "For instance, lncRNA DLEU2 is located on chromosome 13q14 and was originally identified as a potential tumor regulator gene." (PMID 31541993, 2019). "lncRNA DLEU2 was widely reported to be taken part in regulating cell proliferation, migration, invasion, and apoptosis by targeting tumor-related genes, including miRNA and mRNA." (PMID 31541993, 2019). "There are a further eight tumor-suppressor genes (DLEU2, CDKN2C, SPRY4, UBE2QL1, LIN9, TFPI2, LRIG3, DUSP1) and six genes serve as both oncogenes and tumor-suppressor genes (FOXO1, CAV1, KLF6, CDK6, PLK1, CTGF)." (PMID 30563222, 2018). "The tumor suppressor microRNAs miR-15a and miR-16-1 are expressed as a microRNA cluster from an intron region of the DLEU2 (Deleted in Lymphocytic Leukemia 2) transcript and influence cell proliferation, survival, and invasion." (PMID 25874209, 2015). "DNA-demethylation of the regions D6 and E6 in CLL cells is directly correlated with an increase in the expression of DLEU1 and DLEU2 and inversely correlated with the expression of the neighboring candidate tumor suppressing protein-coding genes." (PMID 23593011, 2013). "In addition, overexpressed DLEU2 was also reported to promote tumor growth and progression via targeting the EZH2 in HBV-related HCC." (PMID 40625740, 2025). "However, the patient also had vascular invasion and multiple tumor foci, indicating that DLEU2 expression cannot be the sole culprit of death in this patient." (PMID 39397388, 2025). "Furthermore, abnormal expression of lncRNA DLEU2 plays a crucial role in tumor progression and metastasis in pancreatic, lung, and hematopoietic malignancies, suggesting that lncRNA DLEU2 is involved in diverse cancers with similar functions." (PMID 38296962, 2024). "Our findings demonstrate that inhibition of the lncRNA DLEU2/ROR1 pathway may complement the antitumor or anti-metastatic activity by eliminating drug-resistant CSCs or inhibiting tumor cells from acquiring CSC-like characteristics." (PMID 38296962, 2024). "Abnormal expression of DLEU2 may provide new clues into the mechanism of tumor formation, indicating that DLEU2 may be a biomarker for cancer diagnosis." (PMID 37095423, 2023).